TIGIT (T cell immunoreceptor with Ig and ITIM domains)
Diseases named in the same sentence as TIGIT in open-access papers (continued):
Sharing a sentence is not in itself a finding about the gene and the disease.
melanoma (continued). "Several monoclonal antibodies blocking TIGIT interaction with PVR are in different phases of clinical trials and have already shown exciting results in non-small-cell lung cancer and melanoma." (PMID 37760586, 2023). "In melanoma patients, CD8+ TILs highly expressed TIGIT together with PD-1, this high-TIGIT expression was consistent with that observed in NSCLC patients." (PMID 37670328, 2023). "This indicates preserved proinflammatory potential of DP cells and is supported by transcriptomic data in circulating PD-1+TIGIT+ CD8+ T cells, mostly co-expressing LAG-3, in melanoma and Merkel cell carcinoma." (PMID 37794264, 2023). "In both melanoma models and patients, TIM-3 and TIGIT define subsets of NK cells showing an exhausted phenotype and impaired cytotoxic functions; accordingly, TIM-3 and TIGIT inhibition reverses NK cell exhaustion and dysfunction." (PMID 37298470, 2023). "Our results show that increased expression of ITGAL is associated not only with PD1 and CTLA4, but also with other potential melanoma checkpoints (LAG-3, Tim-3, and TIGIT)." (PMID 37388230, 2023). "Based on their strong positive correlations with CD47 mRNA expression in the TCGA melanoma data, we selected MCL1, CD40LG, TNF, and TIGIT to examine their regulation by CD47 signaling in human Jurkat T lymphoblast cells." (PMID 36768931, 2023). "The most recent TIGIT inhibitor, EOS-448, is being examined in combination with other agents in patients with melanoma and other solid tumors to evaluate its safety and efficacy (NCT05060432)." (PMID 37345056, 2023). "TIGIT expression was also observed on tumour infiltrating CD8+ T cells and NK cells in mouse models of melanoma, colon cancer, breast cancer, and fibrosarcoma." (PMID 35327475, 2022). "TIGIT binds to two ligands, CD155 and CD112, that are expressed by melanoma cells and antigen-presenting cells to downregulate T and NK cell functions." (PMID 36125617, 2022). "We analyzed nine CpG sites within the TIGIT promoter flanks (CpG1-7), within the gene body (CpG8), and within the 3’UTR (CpG9) in melanomas from the TCGA cohort." (PMID 35410311, 2022). "In melanoma, CD8+ TILs with decreased DNAM-1 expression and TIGIT upregulation mostly express also PD-1." (PMID 36497240, 2022). "In a melanoma mouse model, PET using 89Zr-labeled anti-TIGIT antibody can sensitively detect the expression of TIGIT on tumor-infiltrating lymphocytes." (PMID 35471681, 2022). "For example, TIGIT expression on the CD8+ T-cells decreased in the influence of pancreatic CAFs-derived secretome, while in reverse, melanoma CAF−derived factors containing l−arginase induce increased expression of TIGIT and BTLA in CD8+ T-cells." (PMID 36275750, 2022). "TIGIT promoted CD8+ T-cell exhaustion in colorectal cancer and impaired antigen-specific T cells in melanoma." (PMID 35844584, 2022). "TIGIT is highly expressed on CD8+ tumor-infiltrating lymphocytes (TILs) in various tumors, such as gastric cancer, colon cancer, breast cancer, melanoma, and NSCLC." (PMID 36189222, 2022). "Dual PD-1/TIGIT blockade also enhances the proliferation and function of tumor antigen-specific CD8+ T cells and TILs isolated from melanoma patients compared to single PD-1 blockade." (PMID 36125617, 2022). "Both PD-1 (mainly on CD8+ T cells) and TIGIT (on CD8+ T cells, Tregs and NK cells) are expressed in over 70% of melanoma TMEs." (PMID 36497240, 2022). "The produced decision tree consists of three informative genes (KLK8, TIGIT, and TRIM63) along with a threshold level for each gene, which together provide a simple method for classifying melanoma tumors into one of the four subgroups." (PMID 33564068, 2021). "TIGIT is expressed on human tumor-infiltrating CD8+ T cells, NK cells, Th and Treg cells in melanoma, NSCLC, colon cancer, HCC, gastric cancer, glioblastoma and hematological malignancies." (PMID 34367161, 2021).
melanoma (continued). "TIGIT expression is upregulated and DNAM-1 expression in CD8+ TILs is decreased in melanoma and AML patients, indicating the role of a TIGIT/DNAM-1 imbalance in tumor progression." (PMID 34433460, 2021). "A review article noted that preclinical studies established that anti-TIGIT and anti-PD-1 combination therapies enhance the expansion of CD8+ TILs and trigger cytotoxic responses to melanoma more effectively relative to checkpoint blockade alone." (PMID 33801815, 2021). "Several groups have consistently reported that TIGIT is highly expressed on CD8+ TILs in many cancers, such as nonsmall cell lung cancer, colon cancer, melanoma, and acute myelogenous leukemia." (PMID 34433460, 2021). "Emerging studies have shown that cancer cells not only express inhibitory IC ligands but also inhibitory IC receptors including PD-1, TIGIT and TIM-3 in OAC, melanoma, pancreatic, gastric cervical, lung, ovarian, endometrial and colorectal cancer." (PMID 33765543, 2021). "TIGIT expression is also enhanced on CD4+ and CD8+ T cells that infiltrated melanoma tumors in mice afflicted by B16F10 melanoma tumors." (PMID 32902664, 2021). "The TIGIT/CD155 axis mediates resistance to ICIs in patients with melanoma with an inflamed TME, promoting the development of TIGIT blockade therapies in such patients with cancer." (PMID 34795004, 2021). "In vivo blockade of TIGIT or CD96 using Abs inhibited tumor growth and metastasis in an NK cell-dependent manner and thus improved the overall survival in melanoma and experimental or spontaneous lung metastasis models." (PMID 32714324, 2020). "Further supporting a role of obesity-induced T cell exhaustion in melanoma is the increase in gene expression of inhibitory molecules PD-1, TIGIT, EOMES, TIM3 and LAG3 found in melanoma patients with a high body mass index (BMI)." (PMID 32549336, 2020). "The dual inhibition of TIGIT and PD-1 has been further investigated in an attempt to elicit potent antitumor CD8+ T cell responses in patients with advanced melanoma." (PMID 32903786, 2020). "In malignant melanoma, the co-expression of PD-L1, LAG-3, TIM-3 and TIGIT was demonstrated to induce CD8+ TILs with most exhausted phenotype." (PMID 32235439, 2020). "Our findings are in line with a recent report in which melanoma cells expressing PVR control anti-melanoma CTL responses via the interaction between TIGIT and PVR in the effector phase by a suppression of cytokine release from melanoma-specific CTL." (PMID 29855615, 2018). "In human melanoma, tumor-specific CD8+ T cells in peripheral circulation and CD8+ TIL were found to express both TIGIT and PD-1 and furthermore, TIGIT was upregulated in response to PD-1 blockade." (PMID 29276510, 2017). "Studies that investigated coinhibitory receptor expression by NY-ESO-1-specific CD8+ T cells from advanced melanoma patients have shown that coexpression of PD-1 with TIM-3, BTLA and TIGIT indicate T cell dysfunction and exhaustion." (PMID 29033936, 2017). "Dual PD-1/Tim-3 and dual PD-1/TIGIT blockades enhanced the expansion and function of TA-specific CD8+ T cells isolated from patients with advanced melanoma." (PMID 27461275, 2016). "Similarly, TIGIT blockade synergizes with CTLA-4 inhibition by restoring CD226 co-stimulatory signaling, improving progression-free survival in melanoma models." (PMID 40567374, 2025). "The T cell immunoreceptor with Ig and ITIM domains (TIGIT)/CD55 axis contributes to immune suppression by suppressing T cell recruitment and activation, thereby reducing the immune system’s ability to target melanoma cells effectively." (PMID 40872475, 2025). "Testing 75 SLNs and regional LNs from patients with melanoma revealed a negative correlation between the CD226:TIGIT ratio on CD8 T cells and the DCCD (P < 0.0001, Pearson’s correlation)." (PMID 40379833, 2025).
melanoma (continued). "Additionally, co-expression of TIGIT and PD-1 on circulating CD8 T cells has been shown to predict response to PD-1 blockade in patients with melanoma and Merkel cell carcinoma." (PMID 40944710, 2025). "The expression of PD-1 and TIGIT in the CX3CR1+ subset was substantially lower than that in the CX3CR1− subset in the tumor microenvironment, in agreement with the scRNA-seq analyses of human melanoma." (PMID 38881188, 2024). "Moreover, NK cells with MAP4K1 expression exhibited significantly increased exhaustion signature (PDCD1, TIGIT, HAVCR2, and LAG3) in melanoma tissues (GSE120575 and GSE72056)." (PMID 38828677, 2024). "Finally, we explore the impact of CD155 and its receptors DNAM-1, TIGIT, and CD96 on immune cells, especially in the context of the melanoma tumour microenvironment and anti-cancer immunotherapies." (PMID 38893071, 2024). "TIGIT up-regulation has been observed in various malignancies, including melanoma, breast cancer, non-small-cell lung carcinoma (NSCLC); indeed TIGIT expression on peripheral blood CD8+ T cells of various cancer patients has been associated with metastases and poor survival." (PMID 37576404, 2023). "Considering that CYTL1 may be a potential oncogene in melanoma, it was assessed how CYTL1 interacted with PDCD1, CD274, HAVCR2, TIGIT, SIGLEC15, CTLA4, LAG3, and PDCD1LG2." (PMID 37745303, 2023). "A study showed that sole TIGIT blockade or TIGIT/PD-1 blockade decreased the tumor burden through NK cell activation, which enhanced CD8 T cell-mediated antitumor immune responses in B16 melanoma and CT26 lung metastatic mouse models." (PMID 36829496, 2023). "Besides, highly infiltrated TIGIT+ Treg cells and high levels of CD155 jointly mediate the enhanced inhibitory function of Treg cells in the tumor microenvironment of melanoma." (PMID 35433470, 2022). "Anti-TIGIT mAb treatment has been shown to escalate the proliferation, cytokine production, and degranulation of bone marrow CD8+ T cells from MM patients and peripheral blood CD8+ T cells from melanoma patients." (PMID 36189222, 2022). "The translational potential of dual PD-1/TIGIT inhibition has already been demonstrated; it increases the proliferation and function of intratumoral antigen-specific CD8+ T cells in melanoma patients to an extent that is much more dramatic than a single blockade." (PMID 36189222, 2022). "NY-ESO-1-specific CD8+TILs express low levels of CD226 and high levels of TIGIT and PD-1 in melanoma patients, but this imbalance is not found in circulating CD8+T cells regardless of specificity for NY-ESO-1." (PMID 33670993, 2021). "Furthermore, co-blockade of PD-1 and TIGIT increased the in vitro proliferation, cytokine production and anti-tumor function of CD8+ TILs from HCC and melanoma patients." (PMID 34367161, 2021). "In contrast to colorectal cancer in which tumor-infiltrating NK cells displayed higher TIGIT expression than peri-tumoral NK cells, no major difference in TIGIT expression was noted on circulating NK cells between healthy donors and melanoma patients." (PMID 34885076, 2021). "In addition, we report for the first time that the TIGIT/CD155 axis can contribute to such inflamed resistance, including both primary and acquired resistance, in another large melanoma cohort." (PMID 34795004, 2021). "Furthermore, TIGIT blockade increases the capacity for proliferation and degranulation of CD8+TILs from advanced melanoma patients upon TCR stimulation using autologous non-CD3 cells and anti-CD3 mAbs." (PMID 33670993, 2021). "In in vitro studies, concomitant TIGIT and PD-1 blockade additively increased proliferation, cytokines production and degranulation of both tumor antigen-specific CD8+ T cells and CD8+ TILs from advanced melanoma patients." (PMID 31554169, 2019). "In addition, targeting TIGIT and PD-L1 on tumour-infiltrating CD8+ T cells in patients with advanced melanoma synergistically improves potent anti-tumour responses." (PMID 31337800, 2019).
melanoma (continued). "Secondly, different from PD-1 on melanoma cells, intrinsic TIGIT does not affect the proliferation of tumor cells in vitro." (PMID 30555485, 2018). "Interestingly, co-blockade of TIGIT and PD-1 on CD8+ T cells was recently shown to be less effective on tumor infiltrating lymphocytes as compared to circulating melanoma-specific CD8+ T cells in patients with metastatic melanoma." (PMID 28084312, 2017). "In addition, targeting TIGIT and PD-L1 on CD8+ tumor infiltrating lymphocytes in patients with advanced melanoma synergistically improves potent anti-tumor responses." (PMID 26741490, 2016). "We performed immunofluorescent analysis of TIGIT positivity on CD3+ T cells on cohorts of primary RCC tumors and matched adjacent normal kidney samples, matched RCC primary and metastatic tumors, and cohorts from four other tumor types (melanoma, NSCLC, cervical, and head and neck cancer)." (PMID 39105820, 2024). "During treatment, higher proportions of 41BB+ Tconv cells, LAG3+ γδ2–T and TIGIT+ iNKT cells were observed in R compared to NR patients, while frequencies of GITR-expressing γδ2–T and iNKT, 41BB-expressing NKbright and CD27-expressing NKdim cells were decreased in responder melanoma patients." (PMID 39687620, 2024). "Clinical data indicated that PD1 and T cell Ig and ITIM domain (TIGIT) inhibitors regulated the expansion and function of tumor antigen-specific CD8+ T cell in melanoma patients, indicating that combining multiple checkpoint inhibitors could be a viable approach to prevent T cell exhaustion." (PMID 36726126, 2023). "However, blocking TIGIT alone cannot reverse the cytotoxic effect of NK cells infiltrated in melanoma, while activated NK cells can induce TIGIT expression." (PMID 35433470, 2022). "TIGIT has proven to be of clinical interest due to its dual expression on tumor and immune cells, such as NKs and CD8+ tumor infiltrating T cells, and the positive correlation between TIGIT levels and PD-1 expression on human melanoma infiltrating CD8+ T cells." (PMID 36551637, 2022). "Interestingly, both TIGIT and DNAM-1 expression could be rescued by IL-15 treatment, and combination with TIGIT blockade further enhanced human NK cell killing of the melanoma cell line FO-1." (PMID 34503073, 2021). "Immunohistochemistry studies have situated CD96 as a marker of poor prognosis and immune exhaustion in HCC as well as in other cancer types like melanoma, gastric cancer, and pancreatic cancer; some of which also identified TIGIT as a negative prognostic marker." (PMID 33498698, 2021). "Melanoma cells induce Tregs to overexpress various inhibitory checkpoint receptors, including programmed cell death protein 1 (PD-1), CTLA-4, T cell immunoglobulin and mucin domain-containing protein 3 (TIM-3), LAG-3, and T cell immunoglobulin and ITIM domain (TIGIT)." (PMID 34806028, 2021). "Notably, in one study on advanced melanoma, TIGIT was upregulated and coexpressed with PD-1 in the majority of CD8+ TILs, and a dual blockade with TIGIT and PD-1 blockade additively increased proliferation, cytokine production, and degranulation in tumor antigen-specific CD8+ T cells." (PMID 33801815, 2021). "Here, we show that, after intravenous injection with sCD155-producing B16/BL6 melanoma, the numbers of tumor colonies in wild-type (WT), TIGIT knock-out (KO), or CD96 KO mice, but not DNAM-1 KO mice, were greater than after injection with parental B16/BL6 melanoma." (PMID 32040157, 2020). "Chauvin JM and colleagues confirmed that TIGIT and PD-1 co-blockade could improve the expansion and function of circulating tumor specific CD8+ T cells and tumor infiltrating CD8+ T cells thus enhancing CD8+ T cell responses to melanoma." (PMID 30555485, 2018). "Interestingly, CD8+ TILs downregulated CD226, the costimulatory counterpart to TIGIT, supporting an imbalance of TIGIT/CD226 expression in metastatic melanoma, which may contribute to melanoma-induced T cell dysfunction." (PMID 27461275, 2016).
melanoma (continued). "Furthermore, emerging research has identified other biomarkers, including TIGIT, VISTA, and LAG-3, as potential targets in future immunotherapies, and some studies have already begun testing these drugs in treating cancers such as melanoma, yielding promising results." (PMID 40075698, 2025). "Importantly, CX3CR1 expression in human melanoma-infiltrating CD8+ T cells was inversely correlated with the expression of PDCD1, TIGIT, and HAVCR2, which is consistent with our previous flow cytometric analyses of mouse melanoma-specific CD8+ T cells and human melanoma CD8+ TILs." (PMID 38881188, 2024). "Moreover, TIGIT expression has been found to positively correlate with PD-1 and PD-L1 density in the tumor microenvironment (TME), highlighting the synergy between the two immune-checkpoint axes, as seen in lung squamous cell carcinoma, lung adenocarcinoma, and melanoma." (PMID 37109579, 2023). "Deregulation of the TIGIT/CD226/CD155 axis was described in several tumors: TIGIT+ tumor infiltrating CD8+ T cells could be detected in small-cell lung cancers, colorectal cancers and melanoma, and TIGIT inhibition was recently shown to increase T cell functions of melanoma specific CD8+ T cells." (PMID 32155826, 2020). "TIGIT blockade is being evaluated in multiple clinical trials, including phase III studies for advanced non-small cell lung cancer (NSCLC) and melanoma, and phase II basket trials for solid tumors, although none treating RCC specifically (NCT04294810, NCT05665595, NCT04693234, NCT03708224)." (PMID 39105820, 2024). "The two agonists of TIGIT, CD155 (also known as poliovirus receptor [PVR]) and CD112 (alternatively termed as PVRL2 or nectin-2), are widely expressed by immune, non-immune, and tumor cells, including melanoma cells." (PMID 38617537, 2024). "While we were able to indicate a prognostic value of TIGIT methylation and mRNA expression even in ICB-treated melanomas, it is not clear yet, if TIGIT methylation and mRNA expression has the potential to predict response to ICB or if it is rather only prognostic under ICB treatment." (PMID 35410311, 2022). "PD-1 and TIGIT double-positive T cells are predictive of enhanced anti-PD-1 activity as has been shown in melanoma and merkel cell carcinoma, but without the presence of DNAM-1 (marking the activation state of CD8+ T cells), there is no durable response to anti-PD-1 or indeed anti-TIGIT blockade." (PMID 37325585, 2023). "Interestingly, in the same study, TIGIT blockade as a single treatment failed to reverse NK cells dysfunction, while together with IL-15 had reversed CD155-mediated NKs exhaustion and had inhibited experimental melanoma metastasis in vivo." (PMID 35656508, 2022).